CD4 (CD4 molecule)
Diseases named in the same sentence as CD4 in open-access papers (continued):
Sharing a sentence is not in itself a finding about the gene and the disease.
COVID-19 (continued). "Children with COVID-19 had significantly higher CD3+ CD8+ T cells (p = 0.004) and, on the other hand, had significantly lower CD4+/CD8+ ratio (p = 0.042) compared with age-matched and gender-matched healthy children." (PMID 34976886, 2021). "Very low CD3, CD4, and CD8 cell counts indirectly support the need to decrease doses of immunosuppressive agents in patients with COVID-19, especially in those who have received antithymocyte globulin, which decreases all T-cell subsets for many weeks." (PMID 34063052, 2021). "Here we report virus-specific CD4+ and CD8+ T-cell memory in recovered COVID-19 patients and close contacts." (PMID 33741972, 2021). "This analysis showed reduced fractions of lymphocyte subsets (CD4, CD8, NK and B-cells) and increased monocytes and granulocytes in COVID-19 patients, which is in line with previous and own measurements with flow cytometry." (PMID 34502212, 2021). "To estimate, in how far expression of α4β7 integrin on overall memory CD4+ T cells reflects α4β7 expression of SARS-CoV-2-induced memory T cells, we used a cocktail of viral epitopes to stimulate PBMCs from COVID-19 patients." (PMID 33959123, 2021). "As mentioned, severe cases of influenza and COVID-19 share a similar immune response, including a reduced number of circulating CD8 + and CD4 + T cells and increased amounts of proinflammatory cytokines." (PMID 34749737, 2021). "Although some decreases were reported in CD4+ T cells, CD8+ T cells, B cells, and NK cells in the COVID-19 patients, knowledge on the role of lymphocyte subsets in humoral and cellular immune regulations in these patients is limited yet." (PMID 34225645, 2021). "Despite the evaluated levels of circulating memory Tfh cells in both the lymph nodes and spleen of patients with COVID-19, Tfh cells with different phenotypes, CD4+ICOS+, CD4+ CXCR5+, and CD4+ Bcl-6+, were present at decreased levels." (PMID 34696395, 2021). "While higher frequencies of neutrophils and effector memory (EM)-like CD4+ and CD8+ T-cells were found in COVID-19 respiratory samples, higher antibody levels also correlated with activated cellular immunity." (PMID 34462740, 2021). "An overall decline of lymphocyte subsets including CD4+ T cells, CD8+ T cells, B cells, and NK cells has been reported in severe and deceased COVID-19 patients." (PMID 34210280, 2021). "During analysis of the CD38+ marker on CD4+ cells we observed that there were lower CD4+ CD38+ cells in COVID-19(+) patients compared to the HC group and COVID-19(−) virus group." (PMID 33419040, 2021). "Our previous work has demonstrated that serum concentrations of IL-6 are negatively correlated with circulating CD4+ and CD8+ T cell counts in COVID-19 patients, but little is known about the source of IL-6." (PMID 33995382, 2021). "Subsequent studies using peptide-HLA multimers to define SARS-CoV-2-specific T cell responses provide now enough evidence to show that robust CD4+ and CD8+ T cells can be elicited during BNT162b2 mRNA COVID-19 vaccination." (PMID 35004764, 2021). "Here, we report a comprehensive single-cell transcriptional and TCR landscape of CD4+ T cells collected from the BALF and the peripheral blood of patients with severe COVID-19." (PMID 33622974, 2021). "In the COVID-19 group, the majority of HIV-1–infected patients were on ART (74.2%) and had a median CD4 count of 132 cells/mm3 and a median log viral load less than 1.3 log mRNA copies/mL." (PMID 33945513, 2021). "The response of CD4+ T cell to SARS-CoV-2 S protein was also correlated with the specific IgG and IgA titers in patients who recovered from COVID-19." (PMID 32916812, 2020). "Impaired cellular functionality in CD4+ and CD8+ T cells has been observed in severe COVID-19 cases along with generally lower interferon γ (IFNγ) and tumor necrosis factor α (TNF-α) production." (PMID 33362779, 2020).
COVID-19 (continued). "We performed a comprehensive analysis of the ex vivo CD39 and CD73 expression pattern on CD4+ T, CD8+ T, natural killer T (NKT) and natural killer (NK) cells of COVID-19 patients using a 16-color flow cytometry panel." (PMID 32707842, 2020). "We have found a decreased proliferation index among TE CD4+ and CD8+ T lymphocytes from COVID-19 patients." (PMID 32632085, 2020). "The expression level of CD4, CD25, and Foxp3 was significantly downregulated 5-, 2-, and 3-fold, respectively, among COVID-19 patients in comparison to healthy controls (P-value < 0.0001)." (PMID 33244382, 2020). "In COVID-19 patients, OX40 expression had increased remarkably on CD4+ T-cells, especially in severe ICU patients." (PMID 34676125, 2020). "The maturation and formation of CD4+ T lymphocytes depend on the function of human thymus tissue cells, which can express the ACE2 receptor, suggesting that the damage to human thymus cells caused by 2019-nCoV may be a cause of the decrease in peripheral blood lymphocytes in patients with COVID-19." (PMID 32976531, 2020). "CD3+, CD4+, and CD8+ T cell counts are significantly lower in patients with severe COVID-19 when compared to those with mild disease, with numbers increasing significantly in subjects who respond clinically to anti-viral treatment." (PMID 33123152, 2020). "This is consistent with the results of our previous research that indicated the lower levels of CD3+ T cell, CD4+ T cell, CD8+ T cell, B cell (CD19+) and NK cell (CD16+ 56+) in severe COVID-19 cases and their correlations with the course of those cases." (PMID 33106442, 2020). "The authors described an increase in antibody-secreting cells, follicular helper T cells, activated CD4+ and CD8+ T cells, and immunoglobulin IgG- and IgM-binding COVID-19 in the blood before symptomatic recovery." (PMID 32695683, 2020). "Severe or critical COVID-19 patients also exhibited defective adaptive immune response evidenced by significantly lower levels of lymphocytes and their subsets (CD3, CD4, CD8)." (PMID 33002041, 2020). "Further study is needed to investigate the mechanism by which CD4+ and CD8+ T cell numbers decrease in the peripheral blood of COVID-19 patients." (PMID 32976531, 2020). "Compared with mild COVID-19 patients, severe COVID-19 patients had lower peripheral CD3+ T lymphocyte count and CD3+ CD4+ T lymphocyte count, especially CD3+ CD8+ T lymphocytes and CD16+ CD56+ NK cells." (PMID 32669467, 2020). "PLWH admitted with COVID-19 must continue to receive ART and appropriate OI prophylaxis if CD4 T cell counts decrease." (PMID 33083001, 2020). "In a recent study of antigen-specific CD4 and CD8 T cell responses in acute and convalescent COVID-19 patients, a substantial Th1 and TFH fraction was observed, with little Th2 or Th17 responses." (PMID 33262067, 2020). "Here, we studied 10 COVID-19 patients who required admission to an intensive care unit and detected SARS-CoV-2-specific CD4+ and CD8+ T cells in 10 out of 10 and 8 out of 10 patients, respectively." (PMID 32591408, 2020). "In contrast, the percentages of several CD4+ T cell subsets, including CD4-Naive, CD4-LTB, CD4-ICOS, Treg-CTLA4, as well as cycling T cells, were significantly increased in severe COVID-19 than those in mild COVID-19." (PMID 33101705, 2020). "Last, STING over-activation induces progressive CD4+ and CD8+ T lymphopenia in SAVI syndromes, which parallels what is observed in severe COVID-19." (PMID 33335532, 2020). "An important decrease not only in CD4+, but also in CD8+ T lymphocyte count was previously reported in critical patients, pointing to the importance of a dysregulated immune response in COVID-19 pathogenesis." (PMID 33182268, 2020). "Higher levels of IL-6 and IL-10 as well as lower levels of CD4+ and CD8+ T cells found in COVID-19 patients correlated with the severity of the disease." (PMID 32944387, 2020).
COVID-19 (continued). "This phenomenon is also the main reason why although the number of CD4+ Th cells in the peripheral blood significantly decreased, the plasma levels of TNF-α and IL-6 significantly increased in patients with COVID-19." (PMID 32976531, 2020). "In the two cases of severe COVID-19, the levels of CRP, PCT, serum ferritin, IL-6, and IL-10 were significantly increased, whereas the numbers of CD3+, CD4+, CD8+ T lymphocytes, and CD16 + CD56 natural killer cells were decreased." (PMID 32574284, 2020). "For hospitalized patients with COVID-19, lymphocyte, CD3+ and CD4+ counts that marked decrease suggest a poor outcome." (PMID 33125396, 2020). "Here the authors use multi-color flow cytometry to characterize CD4+ and CD8+ T cells in peripheral blood from 39 COVID-19 patients in Italy to report altered T cell activation, function and polarization." (PMID 32632085, 2020). "In early stages, Th2 differentiation are noticed in both severe COVID-19 and SAVI syndromes; then, CD4+ and CD8+ T cells functional exhaustion/senescent patterns due to TCR hyper-responsiveness are observed." (PMID 33335532, 2020). "CD25 expression occurs mostly in CD4+ T-cells, and therefore, these CD25+ hyperactivated T-cells are likely to be the source of the elevated serum soluble CD25 in severe COVID-19 patients." (PMID 33178221, 2020). "It has also been shown that the CD4+ and CD8+ T cell response is cross-reactive between the N proteins of both SARS and COVID-19 patients, with immunity to COVID-19 remaining for patients originally exposed to SARS-CoV." (PMID 33028689, 2020). "Activated CD4+ T cells reactive against at least one of the spike peptide pools of SARS-CoV-2 were found in 75% of unexposed HC, 81% of post COVID-19 and in 75% and 63% of the HCoVs, respectively." (PMID 33424856, 2020). "The upregulation of the co-inhibitory receptors LAG-3 and TIM-3 was more pronounced on CD8+ T cells in COVID-19 patients while malaria patients showed especially high expression of LAG-3 and TIM-3 on CD4+ T cells." (PMID 32983106, 2020). "CD4+ and CD8+ T cells from convalescent COVID-19 patients can recognize a range of SARS-Cov-2 epitopes, and the S protein represents a major target." (PMID 32989130, 2020). "On the other hand, the numbers of CD4+ T cells, CD8+ T cells, B cells, and NK cells normalize in patients who have recovered from the COVID-19." (PMID 33167401, 2020). "We performed immune profiling of the T helper (Th) CD4+ and T CD8+ cell compartments in peripheral blood of 144 COVID-19 patients using multiparametric flow cytometry analysis." (PMID 33324414, 2020). "In sum, we quantified and phenotyped SARS-CoV-2-specific CD4+ T cells, SARS-CoV-2-specific CD8+ T cells, and antibody responses in both acute and convalescent COVID-19 cases." (PMID 33010815, 2020). "Sustained decrease in total T (CD3+) cells, Th (CD4+) cells, Tc (CD8+) cells, and NK (CD16+CD56+) cells was often observed in the current cohort of COVID-19 patients." (PMID 33061829, 2020). "We detected SARS-CoV-2-specific CD4+ and CD8+ T cells in 10/10 and 8/10 COVID-19 patients, respectively." (PMID 32591408, 2020). "We also compare the expression of exhaustion markers PD-1 and Tim-3 on the surface of CD4+ and CD8+ T cells from COVID-19 patients and healthy controls." (PMID 32425950, 2020). "During SARS-CoV-1 infection, the occurrence of lymphopenia with drastically reduced numbers of both CD4 and CD8 T cells in moderate and severe COVID-19 cases has been described in several current reports." (PMID 32793246, 2020). "Other highly-ranked genes included proposed prognostic factors (CXCL10, CD4, CD3E) and investigational therapeutic targets (IL1A) for COVID-19." (PMID 33339864, 2020). "Differences in CD4+ and CD8+ T cell counts between the survival and fatal cases became significant between 2 to 4 weeks after COVID-19 onset (P <0.05 for all)." (PMID 33362779, 2020).
COVID-19 (continued). "Early pathological findings of COVID-19 patients with ARDS, showed not only reduced counts of peripheral CD4+ and CD8+ T cells, but that remaining T cells were found in a hyperactivated state, with high proportions of HLA-DR and CD38 double-positive fractions." (PMID 33013871, 2020). "Consistent with recent case reports, we observed increased activation of both memory CD4+ and CD8+ T cells in severe COVID-19+ individuals compared to other study groups." (PMID 32669287, 2020). "In severely affected COVID-19 patients, the proportions of IFN-γ yielding CD8+T and CD4+T cells were enhanced as compared to mild case which lead to ‘cytokine storm’." (PMID 32916821, 2020). "Evaluating the expression level of CD4+ FoxP3+ CD25+ T cells and IL-6 in peripheral blood samples of hospitalized COVID-19 patients." (PMID 33244382, 2020). "Recent communications from others also reported the presence SARS-CoV-2−reactive CD4+ and CD8+ T cells in both acute and convalescent COVID-19 patients." (PMID 32913053, 2020). "Representative data from mild-COVID-19 BAL were mostly consistent of lung macrophages (cluster −0, −1, and −2), CD19, CD4, CD4 Th1, CD8, and NK cells, as well as lung and bronchial epithelial cells." (PMID 33138195, 2020). "It has been shown Tregs (Foxp3+, CD3+, CD4+, CD25high, CD127low) are significantly decreased in severe SARS-CoV-2 patients, suggesting a possible role in hyper-inflammatory responses in COVID-19 pathogenesis." (PMID 33302366, 2020). "Analysis of the BALF transcriptome showed that T and NK cells are increased in COVID-19 patients, compared to healthy controls, which according to their gene expression can be classified in NK, CD8, CD4, Tregs, and proliferating cells." (PMID 32612615, 2020). "In COVID-19 patients we found high frequencies of single-positive PD1−LAG-3+ and PD1−TIM-3+ CD8+ and CD4+ T cells and fewer double-positive PD1+LAG-3+ and PD1+TIM-3+ T cells." (PMID 32983106, 2020). "We found that the CD4+ T cells in the peripheral blood were decreased in individuals infected with COVID-19 but that the levels of TNF-α and IL-6 in the plasma, which can be produced by CD4+ T cells, were significantly increased." (PMID 32976531, 2020). "Using multiple experimental approaches, CD4+ and CD8+ T cell and antibody responses specific to SARS-CoV-2 were observed through all COVID-19 cases." (PMID 32595358, 2020). "In this regard, CD4+ T and CD8+ T were strongly reduced in patients with severe COVID-19 compared with those in patients with mild disease." (PMID 32490931, 2020). "Decreases in the total number of T cells (CD3+CD19-), helper T cells (CD3+CD4+), suppressor T cells (CD3+CD8+) and NK cells (CD3−/CD16+CD56+) were also observed in the COVID-19 patients." (PMID 33365277, 2020). "Overall the frequencies of CD38+ and HLA-DR+CD38+ memory CD4+ and CD8+ T cells in severe COVID-19 were elevated compared to HD (p<0.01 for all cases), and frequency of HLA-DR+ CD4+ and CD8+ T cells was also directly associated with APACHE III scores." (PMID 32669287, 2020). "In this report, we retrospectively reviewed the numbers of total T cells, CD4+, CD8+ T cell subsets in a total of 499 COVID-19 patients." (PMID 32425950, 2020). "Compared to healthy controls, COVID-19 patient CD8+ T cells and CD4+ T cells activated in vitro produce more IL-17, indicating skewing toward a Th17 phenotype." (PMID 32922297, 2020). "Similar to SARS and MERS, the number of total T cells, CD4+, and CD8+ T cells was significantly diminished in COVID-19 patients in comparison to healthy controls and positively correlated with the severity of the disease." (PMID 32916812, 2020). "CD4+ and CD8+ T cells in COVID-19 patients gain increased capability to produce IL-17 in vitro, leading to inflammation and neutrophil activation." (PMID 33302366, 2020). "Significant differences in the numbers of CD4+ and CD8+ T lymphocytes between mild and severe/critical COVID-19 cases were described." (PMID 32695683, 2020).
COVID-19 (continued). "Apart from severe lymphopenia, CD4+ and CD8+ T cells from patients with severe COVID-19 exhibited increased expression of CTLA-4 and PD-1 and a high expression of Ki67 as a marker for recent proliferation." (PMID 32937615, 2020). "It is also observed that severe COVID-19 patients present a lower expression of IFN-γ related to the decrease and impaired CD4+, CD8+, and NK lymphocytes." (PMID 32764275, 2020). "In COVID-19 patients, the CD244 and PD-1 expression levels of CD8+ and CD4+ T cells were significantly higher and CD27 expression levels of CD8+ T cells were significantly lower than healthy controls." (PMID 33154753, 2020). "Lymphocytopenia, high exhaustion levels and reduced functional diversity of T-cells (CD4+ and CD8+ T-cells) in peripheral blood is also another clinical feature of COVID-19 patients." (PMID 33708109, 2020). "The effects of GSK-3 were preferentially seen in CD8 CTLs, and to a lesser extent, CD4+ T-cells, the latter contributing to the CRS seen in the more severe clinical manifestations of COVID-19." (PMID 32695123, 2020). "All lymphocytes subsets, including CD4+ T cells, CD8+ T cells, B cells and natural killer cells decreased in COVID-19, especially in patients who develop severe forms." (PMID 32962761, 2020). "In most COVID-19 patients the proportions of T cells subsets can remain within the normal range, but a decrease can exist in CD4+ and CD8+ T cell counts or in CD4+/CD8+ ratio." (PMID 32632085, 2020). "Compared with patients with mild COVID-19, those with severe COVID-19 had significantly higher levels of TNF-α and NT-proBNP, and lower levels of CD4 T cells and albumin globulin." (PMID 33232275, 2020). "All eight patients with CT scan compatible with COVID-19 had undetectable HIV-RNA at the last assessment (within 3 months), six had positive SARS-CoV-2 swabs, two had CD4 cell count below 350/μL at the last assessment." (PMID 32574323, 2020). "The inflammatory infiltrate described in COVID-19 lungs differs from that described in H1N1 influenza lungs, with a predominant infiltration of CD4-positive T cells and a lower number of CD8-positive T cells and neutrophils in COVID-19 lungs." (PMID 32752129, 2020). "In COVID-19 convalescent patients circulating SARS-CoV-2-specific CD8+ and CD4+ T-cells were identified in approximately 70%, and 100%, respectively." (PMID 32806708, 2020). "The persistent reduction of CD4+ and CD8+ T cells was the typical feature of critically ill infant with COVID-19." (PMID 32379199, 2020). "In intensive care (ICU) units, both virus-specific CD4 and CD8 T cells were detected in all COVID-19 patients (at average frequencies of 1.4 and 1.3%, respectively), with phenotypes suggestive of either CD4 central memory, or CD8 effector memory T cells." (PMID 33335532, 2020). "A recent study reported SARS-CoV-2-specific CD4+ T cells in all and CD8+ T cell responses in most COVID-19 patients." (PMID 32793245, 2020). "Peptide pool stimulation enables longitudinal analysis of SARS-CoV-2-specific CD4+ and CD8+ T cells in ICU-admitted COVID-19 patients." (PMID 32591408, 2020). "Stimulation of PBMC collected 14 days post inclusion with the different peptide pools led to consistent detection of CD4+ and/or CD8+ SARS-CoV-2-specific T cells in COVID-19 ARDS patients." (PMID 32591408, 2020). "T cell activation is typically observed during acute viral infections, and as expected we observed increased activation of both CD4+ and CD8+ T cells in severe COVID-19." (PMID 32669287, 2020). "The density of monocytes/macrophages and CD4+ and CD8+ T lymphocytes in the lungs of patients with severe COVID-19 as well as their functional role are key factors to predict the extension of immunopathology." (PMID 33584667, 2020). "Many COVID-19 patients displayed robust CD8 T cell and/or CD4 T cell activation and proliferation and PB responses, though a substantial subgroup of patients (~20%) had minimal detectable responses compared with controls." (PMID 32669297, 2020).